IL18 (interleukin 18)
Diseases named in the same sentence as IL18 in open-access papers (continued):
Sharing a sentence is not in itself a finding about the gene and the disease.
atopic asthma (6 papers, 2008 to 2024). An asthma that is characterized by symptoms that are triggered by an allergic reaction caused by inhaled allergens such as dust mite allergen, pet dander, pollen and mold. "As IL‐18 can modulate IL‐18BP and IL‐18R expression, the role of IL‐18 in atopic asthma is very likely to be decided by the balance of IL‐18/IL‐18BP/IL‐18R expression in response to different allergens." (PMID 28922563, 2018). "The aim of the current study is to investigate the correlation of IL-18 with tryptase in atopic asthma, the role of IL-18 and tryptase in mast cell accumulation and Th2 cytokine release, and interaction between IL-18 and tryptase." (PMID 27069315, 2016). "In order to further understand the contributions of tryptase to atopic asthma we investigate the influence of tryptase on IL-18 release and activities in the current study." (PMID 27069315, 2016). "In conclusion, the correlation between IL-18 and tryptase in the plasma of the patients with atopic asthma suggested a potential connection between them." (PMID 27069315, 2016). "Observations that IFN-γ inducing factor (IL-18) is increased in the airways of patients with atopic asthma support the concept that enhancing the type 1 cytokine cascade can be associated with the development of airways eosinophilia." (PMID 23043798, 2012). "The serum level of theproinflammatory factor IL-18 is known to be significantly elevated in patientswith atopic asthma during the acute phase." (PMID 18949051, 2008). "The secondary analysis using the eQTL cytokines in lung tissue produced qualitatively similar results to the main eQTL analysis, but associations were nominally significant only for IL-18 in relation to FEV1, FVC, and COPD, and IL-16 in relation to atopic asthma." (PMID 39319267, 2024). "Therefore, the aim of this study is to investigate the expression of IL‐18, IL‐18BP and IL‐18R in inflammatory cells of atopic asthma, and influence of allergens on their expression." (PMID 28922563, 2018). "As IL‐18 carries out its biological functions mainly through its receptor IL‐18R 24, and IL‐18BP is a potent endogenous neutralizing antagonist of IL‐18, it is very likely that the role of IL‐18 in atopic asthma is decided by the balance between IL‐18, IL‐18BP and IL‐18R." (PMID 28922563, 2018).
bacterial meningitis (6 papers, 2013 to 2024). Inflammation of the membranes surrounding the brain and spinal cord due to a bacterial infection. "It has been revealed that CSF levels of inflammasome-associated cytokines IL-1β and IL-18 were increased in patients with bacterial meningitis, and that this was associated with complications and unfavorable outcomes." (PMID 35145923, 2021). "IL-23 demonstrated excellent accuracy in diagnosing meningitis, while the combination of IL-23, IL-18 and sRAGE provides a diagnostic algorithm that identified bacterial meningitis with 100% sensitivity and specificity in this cohort." (PMID 29394248, 2018). "We studied associations between inflammasome-associated cytokines IL-1β and IL-18 in cerebrospinal fluid (CSF) of patients with bacterial meningitis and clinical outcome, and pneumococcal serotype." (PMID 23902681, 2013). "In patients with bacterial meningitis, CSF levels of inflammasome associated cytokines IL-1β and IL-18 were related to complications, and unfavorable disease outcome." (PMID 23902681, 2013). "Interleukin-23 (IL-23), interleukin-18 (IL-18) and soluble receptor for advanced glycation end products (sRAGE) possess biologic plausibility, and may be useful as diagnostic markers in bacterial meningitis." (PMID 29394248, 2018). "In conclusion, we have demonstrated that elevations of IL-23, sRAGE and IL-18 are useful adjunctive markers in diagnosis of bacterial meningitis in infants." (PMID 29394248, 2018). "IL-23, alone and in combination with IL-18 and sRAGE, identified bacterial meningitis with excellent accuracy." (PMID 29394248, 2018). "In this study we measured the CSF levels of inflammasome related cytokines IL-1β and IL-18 in a prospective nationwide cohort of community acquired bacterial meningitis and correlated these to clinical data and pneumococcal serotype." (PMID 23902681, 2013). "In addition, the levels of several inflammatory cytokines, such as interleukin (IL)-6, tumor necrosis factor (TNF)-α, IL-1β, and IL-18, are increased in the cerebrospinal fluid (CSF) of patients affected by bacterial meningitis." (PMID 35145923, 2021). "We hypothesized that levels of IL-23, IL-18 and sRAGE are significantly elevated in cerebrospinal fluid of infants with bacterial meningitis as compared to uninfected infants." (PMID 29394248, 2018). "Among them, IL-1β and IL-18 are the main downstream effectors of inflammasome activation, and therefore may also be involved in the neuroinflammatory response to bacterial meningitis." (PMID 35145923, 2021).
chronic myeloid leukemia (6 papers, 2015 to 2025). "In hematological malignancies, polymorphisms restricted only to IL-1β and IL-18 were associated with clinical and pathophysiological characteristics in AML and chronic myeloid leukemia (CML)." (PMID 32733479, 2020). "The aim of this study was to evaluate the relationship between IL-18 gene polymorphisms and susceptibility to chronic lymphocytic leukemias (CLL) and chronic myelogenous leukemias (CML) in Turkish patients." (PMID 26376814, 2015). "Interestingly, NLRP3 and IL-1β mRNA expression levels were shown to be decreased, while IL-18 mRNA expression levels were shown to be increased in chronic myeloid leukemia (CML) compared to controls." (PMID 38397043, 2024). "Similar results were also observed in chronic myeloid leukemia (CML) patients in which genotyping demonstrated that genetic polymorphisms of IL-1β-rs16944, IL-18-rs1946518, and CARD8-rs2043211 were associated with the pathophysiological characteristics and treatment of CML patients." (PMID 30447690, 2018).
dilated cardiomyopathy (6 papers, 2010 to 2024). Cardiomyopathy which is characterized by dilation and contractile dysfunction of the left and right ventricles. "Therefore, the elevation of Il18 expression in the heart, in conjunction with the abnormal hypertrophy in AA affected mice, may be a marker of inflammatory heart disease similar to observations with dilated cardiomyopathy." (PMID 23658656, 2013).
dry eye (6 papers, 2015 to 2025). "Increased production of cytokines IL-1 and IL-18 can amplify the immune reaction of dry eye by stimulating production of cytokines IFN-γ and IL-17 by lymphocytes that cause ocular epithelial disease, including goblet cell loss and corneal barrier disruption." (PMID 37036417, 2023). "Higher levels of inflammasome can in turn activate caspase-1 and the secretion of IL-1β and IL-18, which then induce the inflammatory damage of dry eye." (PMID 25962072, 2015). "The current study confirmed a significant increase in IL-1β and IL-18 mRNA and protein expressions in tears and on the ocular surface of dry eyes." (PMID 25962072, 2015). "The fact that VEGF induces pro-inflammatory cytokines may explain why bevacizumab 0.05% eye drops can improve OSDI scores in dry eye patients, i.e., by inhibiting VEGF-A, itself, and other pain-associated cytokines, including IL-1β, IL-17 and IL-18." (PMID 32502179, 2020). "Further research should focus on the regulatory mechanism of NLRP3 inflammasome in dry eye inflammation; the function of IL-18 in dry eye; and whether inhibition of inflammasome components can serve as a viable target for therapeutic development in dry eye." (PMID 25962072, 2015). "In summary, based on tear samples and conjunctival impression cytology specimens of dry eye patients, we found that the expressions of NLRP3 inflammasome and its downstream inflammatory factors-caspase-1, IL-1β and IL-18 are upregulated in dry eye patients, especially in SSDE." (PMID 25962072, 2015). "But the function of IL-18 in dry eye is still not well understood." (PMID 25962072, 2015). "In the current study, we found that mRNA and protein expressions of NLRP3 inflammasome were upregulated in human dry eyes, especially in SSDE; the downstream inflammatory factors caspase-1, IL-1β, and IL-18 were also elevated in dry eye patients." (PMID 25962072, 2015). "The findings in this study are consistent with those in our previous studies using the DS dry eye model that show levels of IL-18 and IL-1β transcripts do not significantly change over 10 days of DS." (PMID 37036417, 2023).
geographic atrophy (6 papers, 2012 to 2022). "In macular RPE tissue from donors with geographic atrophy that is associated with late AMD, an increase of NLRP3, ASC, Caspase-1, IL-1β, and IL-18 proteins was observed." (PMID 35805159, 2022). "In dry AMD, DICER appears to act via induction of the inflammasome through NLRP3 and secretion of IL-18, leading to RPE cell death, the hallmark of geographic atrophy or dry AMD." (PMID 23230433, 2012). "Interestingly, it was found that there are increased level of NLRP3 protein, IL-1β and IL-18 mRNA in the RPE of donor eyes from individuals with geographic atrophy and neovascular AMD." (PMID 26504591, 2015). "While Il-18’s role in advanced AMD is unclear–there is mixed evidence that it might inhibit CNV and some that it may promote geographic atrophy, Il-1 beta is clearly a pro-angiogenic cytokine." (PMID 30235234, 2018). "Other reports investigating the role of inflammasome in the pathogenesis of AMD observed an increased content of NLRP3, ASC, Caspase-1, IL-1β, and IL-18 protein in RPE tissue from the macula region of donors with geographic atrophy (GA) compared to non-diseased controls." (PMID 35805159, 2022).
glioblastoma (6 papers, 2013 to 2024). The most malignant astrocytic tumor (WHO grade IV). "IF was performed to observe the co-localization of the IL-1β and IL-18 pro-inflammatory cytokines with the GFAP glioblastoma marker." (PMID 35042538, 2022). "This IL-18–stimulated centrifugal migration is an important link between glioblastoma pathology and treatment resistance." (PMID 25963312, 2015). "The accumulation of IL-18 stimulates centrifugal glioblastoma cell migration and then stimulates a new set of microglia at the growing front to synthesize IL-18." (PMID 25963312, 2015). "Recent recognition of the pro-mobility stimulus, interleukin-18, as a driver of centrifugal glioblastoma cell migration allows potential treatment adjuncts with disulfiram and ritonavir." (PMID 25963312, 2015). "In addition, as previously shown, IL18 upregulated the expression of the transcription factor Hif1a, which promoted migration of glycolysis-driven Tregs in a glioblastoma mouse model." (PMID 32687059, 2020). "IL-18 and IL-1beta are both well documented growth facilitating elements in glioblastoma." (PMID 23594434, 2013). "Third, IL18 upregulated genes consistent with an effector phenotype that supports growth and proliferation, such as genes related to fatty acid biosynthesis (Dgat2, Scd2, Hacd3) and Hif1a, which promotes glycolysis as well as migration of Tregs in glioblastoma." (PMID 32687059, 2020). "Thus, there is potential for the suggested combination of disulfiram and ritonavir to reduce an immune response to glioblastoma cells, but if the preponderant effect of IL-18 is to stimulate centrifugal migration, the net effect may well be clinically beneficial." (PMID 25963312, 2015). "The 9-drug regimen CUSP9* designed for recurrent glioblastoma after Stupp protocol treatment already includes both disulfiram and ritonavir for reasons that do not include IL-18 inhibition." (PMID 25963312, 2015).
graft versus host disease (6 papers, 2008 to 2022). An immune system disorder that occurs after allogeneic hematopoietic stem cell transplant and is a reaction of donor immune cells against host tissues. "Transcripts for the pro-inflammatory cytokine Il12A, a mediator of graft versus host disease, Il18 and its receptor, Il21r, and Il1rl1 were lower in NP over FAT cells." (PMID 36406265, 2022). "Administration of IL-18 has been shown to augment adoptive human T cell transfer in a xenogeneic mouse model of graft versus host disease, by diminishing the engraftment of regulatory T cells and enhancing the engraftment of effector T cells and pathology in vivo." (PMID 20003308, 2009). "IL-18 enhanced the engraftment of human CD8+ effector T cells and promoted the development of xenogeneic graft versus host disease (GVHD)." (PMID 18818761, 2008).
Hemophagocytosis (6 papers, 2010 to 2025). Phagocytosis by macrophages of erythrocytes, leukocytes, platelets, and their precursors in bone marrow and other tissues. "IL-18 induces IFN-γ release resulting in hemophagocytosis being the hallmark of MAS." (PMID 36767629, 2023). "Likewise, for CTCLs, elevated serum IL-18 and IL-18 mRNA in skin lesions were reported, while for the rare NK/T-cell lymphomas, high IL-18 serum levels were associated with advanced-stage disease, the presence of hemophagocytosis, and poor treatment outcomes." (PMID 38397043, 2024). "In NK/T-cell lymphoma, high IL-18 serum levels were associated with stage III/IV disease, the presence of hemophagocytosis, and poor treatment outcomes." (PMID 38397043, 2024). "IL-18 itself enhances the production of IFN-γ, which in turn drives hemophagocytosis, i.e., the hallmark of MAS." (PMID 28918754, 2017). "Additionally, they displayed systemic autoinflammation marked by elevated levels of IL-1β, IL-18, and IL-6, alongside cytopenia and hemophagocytosis." (PMID 41116055, 2025). "Since IL-18 plays a major role in perpetuating hemophagocytosis, the failure of IFNγ to induce IL-18BP may constitute a fundamental pathogenetic mechanism." (PMID 20072626, 2010).
hyperandrogenism (6 papers, 2010 to 2025). Excessive secretion of androgens from the adrenal glands or gonads. "Beyond its metabolic effects, IL-18 also influences ovarian function and has been detected in ovarian follicles where increased IL-18 levels are associated with anovulation, menstrual irregularities, and hyperandrogenism." (PMID 40385768, 2025). "Our own investigations have confirmed that augmented abdominal adiposity in PCOS women is associated with IR, diminished sex-hormone-binding globulin (SHBG) levels, hyperandrogenism, and low-grade inflammation (elevated interleukin-18 (IL-18])." (PMID 38275393, 2024). "The results from our two subanalyses with WHtR and FAI showed that IL-18 levels were significantly higher in patients with visceral obesity and hyperandrogenism." (PMID 35263047, 2022). "For further analysis of the relationship between the IL-18 gene promoter polymorphisms and PCOS IR, the PCOS patients were again divided into two sub-groups: PCOS with hyperandrogenism: T ≥ 2.8 nmol/L; PCOS without hyperandrogenism: T < 2.8 nmol/L." (PMID 20964873, 2010).
IgA nephropathy (6 papers, 2012 to 2025). "In renal biopsies of IgA nephropathy patients, the expression levels of IL-18 were positively correlated with both the infiltration of inflammatory cells into the interstitium and the extent of proteinuria." (PMID 33732720, 2021). "In patients with IgA nephropathy, serum IL-18 levels have been reported to correlate significantly with urinary protein excretion, serum creatinine, and the estimated glomerular filtration rate (eGFR)." (PMID 33732720, 2021). "The aim of this research was to investigate the relationship of serum IL-18 levels with histopathological severity and renal prognosis in IgA nephropathy." (PMID 22518072, 2012). "Moreover, the renal survival of IgA nephropathy patients with higher than median serum IL-18 levels at baseline was approximately 20% at the end of the follow-up period (four years), and approximately 80% for total IgA nephropathy patients." (PMID 30717382, 2019). "It was reported that serum IL-18 levels were a potent prognostic factor for IgA nephropathy." (PMID 30717382, 2019). "Notably, serum concentrations of IL-18 in IgA nephropathy patients were significantly elevated compared with healthy controls." (PMID 30717382, 2019). "We suggest that higher serum IL-18 may represent an ongoing inflammatory and fibrotic process in IgA nephropathy, which indicates for intensive therapy from onset." (PMID 22518072, 2012). "The serum IL-18 level may predict the reduction of renal function in patients with IgA nephropathy." (PMID 33732720, 2021). "In patients with IgA nephropathy, circulating levels of NLRP3 inflammasome-derived cytokines, notably interleukin-18 (IL-18) and interleukin-1β (IL-1β), are significantly elevated, underscoring the inflammasome’s central role in disease progression." (PMID 41357229, 2025). "Furthermore, immunohistochemical analyses revealed that the intensity of IL-18 and NLRP3 proteins in renal biopsy samples from patients with IgA nephropathy correlated with the severity of proteinuria." (PMID 30717382, 2019).
Kawasaki disease (6 papers, 2011 to 2023). A rare inflammatory disease characterized by an acute febrile, systemic, self-limiting, medium-vessel vasculitis primarily affecting children. "In contrast with Kawasaki disease, IL-18 is significantly elevated in the acute phase of sJIA, without exception, whereas IL-6 is increased at variable levels." (PMID 35778759, 2022). "IL-18 is also helpful in the differentiation of sJIA and Kawasaki disease because of low levels of serum IL-18 in the latter." (PMID 21749729, 2011). "In severe cases of Kawasaki disease, neopterin and IL-18 may also be increased." (PMID 35778759, 2022).
liver cancer (6 papers, 2008 to 2026). An epithelial or non-epithelial malignant neoplasm that arises from the liver. "In the serum of liver cancer patients, IL‐18 was significantly positively correlated with ALT, GT, LD, PA, and AFU (p < 0.05), indicating that the increase of IL‐18 was related to liver injury." (PMID 33720453, 2021). "In patients with liver cancer, the correlations between serum IL‐18 concentration and alanine aminotransferase, GT, LD, prealbumin, a‐fucosidase, alpha‐fetoprotein, hyaluronic acid, laminin, N‐terminal type III procollagen, and type IV collagen were analyzed." (PMID 33720453, 2021). "Another inflammasome-mediated cytokine, IL-18, is also involved in liver cancer occurrence." (PMID 36289606, 2022). "The average concentration of IL‐18 in the serum of patients with liver cancer was the highest." (PMID 33720453, 2021). "In conclusion, we developed and empirically verified a new and simple ex vivo-expansion protocol using IL-2, IL-12, IL-18, CD16, CD56 and NKp46 for preparing high ratio of NK cells in effector cells (MYJ1633) and demonstrated their cytotoxicity against liver cancer in vitro and in vivo." (PMID 31426763, 2019).